NAA10 (N-alpha-acetyltransferase 10, NatA catalytic subunit)
Diseases named in the same sentence as NAA10 in open-access papers (continued):
Sharing a sentence is not in itself a finding about the gene and the disease.
Arrhythmia (5 papers, 2015 to 2024). Any cardiac rhythm other than the normal sinus rhythm. "Taken together, these data indicate that QT prolongation and risk for arrhythmia in NAA10-related syndrome are caused by a combination of increased INaL and reduced IKs." (PMID 39070617, 2024). "Our study defines novel roles of Nt-acetylation in cardiac regulation and delineates mechanisms underlying QT prolongation, arrhythmia, and cardiomyopathy caused by NAA10 dysfunction." (PMID 39070617, 2024). "Alternatively, the reduced N-acetyl transferase activity of the mutant Naa10 enzymes may have a downstream effect on the regulation of an arrhythmia gene or protein." (PMID 26522270, 2015).
lung carcinoma (5 papers, 2016 to 2025). "We found that NAA10 protein abundance is significantly positively associated with copy number variation and mRNA expression in certain tumor types, notably lung cancer." (PMID 40558489, 2025). "NAA10 was also reported to interact with β‐catenin and promote transcription of cyclin D1 in lung cancer cells." (PMID 35366056, 2022). "They showed significantly decreased levels of NAA10 in 13 out of 15 lung cancer patients with positive lymph node metastasis compared with those with negative lymph node metastasis, suggesting the suppressive role of NAA10 in the tumor metastasis." (PMID 33126484, 2020). "Silencing of Naa10 increases the ability of tube formation, a reflection of vasculogenesis, in both H1299 lung cancer cell line and immortalized mouse endothelial cell line." (PMID 27910960, 2016). "On the other hand, Naa10 expression counter correlates with lung cancer progression and in xenograft experiments Naa10 overexpression suppresses tumor growth and metastasis." (PMID 26666750, 2016). "Among the more than 15 phosphorylation sites identified in the CPTAC dataset, five sites—S167, S171, S174, S190, and S194—exhibited increased phosphorylation levels, even after normalization to total NAA10 protein abundance, in several tumor types, including breast and lung cancers." (PMID 40558489, 2025). "In vitro and in vivo studies have revealed the oncogenic role of NAA10 in lung cancer, demonstrating that NAA10 binds to DNMT1 and positively regulates its enzymatic activity by facilitating DNMT1′s binding to DNA and its recruitment to the promoters of tumor suppressor genes, such as E-cadherin." (PMID 40558489, 2025). "In conclusion, the study report here is the first to unravel Naa10 as the negative regulator of NTN1 and its receptor UNC5B in human lung carcinoma cell lines and caudal half region of E10 mouse embryos." (PMID 27910960, 2016).
prostate carcinoma (5 papers, 2016 to 2025). A carcinoma that arises from epithelial cells of the prostate gland. "Mounting evidence indicates that NAA10 is overexpressed in various cancers, including breast, colon, esophageal, liver, lung, and prostate cancers." (PMID 40558489, 2025). "For example, NAA10 is overexpressed in prostate cancer, where it promotes cell growth in vitro and tumor formation in vivo by acetylating the AR at lysine 618, leading to activation of AR target genes." (PMID 40558489, 2025). "The NAA10–AR (androgen receptor) axis is essential for prostate cancer cell growth." (PMID 35669725, 2022). "Evidence also demonstrated that NAA10 is highly upregulated in various malignancies, including breast, bone, colorectal, liver, lung, and prostate cancers, and that expression level of NAA10 is correlated with the cancer progression, an implication for possibility of NAA10 as a cancer biomarker." (PMID 33126484, 2020). "For instance, NAA10 forms a complex with ADAM9, stabilizing it and promoting prostate cancer invasiveness." (PMID 40558489, 2025).
hypertrophic cardiomyopathy (4 papers, 2020 to 2024). A condition in which the myocardium is hypertrophied without an obvious cause. "In addition to QT prolongation and sudden death, NAA10 variants are associated with hypertrophic cardiomyopathy and congenital heart defects including atrial septal defects, ventricular septal defects, and tetralogy of Fallot5–9." (PMID 39070617, 2024). "Patients with NAA10-related syndrome have variable heart disease phenotypes ranging from hypertrophic cardiomyopathy to congenital heart disease." (PMID 39070617, 2024).
breast carcinoma (3 papers, 2022 to 2025). "Loss-of-function analyses in breast cancer models further indicated that NAA10 plays a critical role in promoting cancer cell growth and survival." (PMID 40558489, 2025). "Additionally, we found that higher NAA10 mRNA expression was significantly associated with tumor aggressiveness and poor prognosis in breast cancer patients." (PMID 40558489, 2025). "In breast cancer, NAA10-mediated acetylation of AURKA at lysine 75 and 125 promotes the proliferation and migration of MCF-7 cells." (PMID 40558489, 2025). "Through its interaction with PIX or STAT5A, NAA10 has been shown to inhibit invasion and metastasis in breast cancer models." (PMID 40558489, 2025). "Another early study in breast cancer revealed that NAA10 directly interacts with tuberous sclerosis complex 2 (TSC2) and mediates its N-terminal acetylation, resulting in TSC2 stabilization, suppression of mTOR signaling, and induction of autophagy." (PMID 40558489, 2025). "Besides, NAA10 inhibits the migration and invasion of breast cancer cells by binding to STAT5a and decreases STAT5a‐stimulated ID1 expression." (PMID 35366056, 2022).
microcephaly (3 papers, 2019 to 2024). A congenital or acquired developmental disorder in which the circumference of the head is smaller than normal for the person's age and sex. "NAA10 has been shown to function abnormally in maxillofacial development, leading to conditions such as microcephaly and abnormal epidermal development." (PMID 38903762, 2024).
Hydrocephalus (2 papers, 2021 to 2024). Hydrocephalus is an active distension of the ventricular system of the brain resulting from inadequate passage of CSF from its point of production within the cerebral ventricles to its point of absorption into the systemic circulation. "Other phenotypic defects present in the Naa10 knockout mice include hydrocephalus, piebaldism, and hydronephrosis, which are consistent with previous findings." (PMID 38713657, 2024). "Although piebaldism has never been reported in humans with OS, all (100%) of the Naa10-/Y and Naa10tm1a/Y mice exhibited hypopigmentation on their belly (upper), with this piebaldism quite varied in its extent but not appearing to correlate in any way with other phenotypes, such as hydrocephaly." (PMID 34355692, 2021).
hydronephrosis (2 papers, 2021 to 2024). Collection of urine in the renal pelvis that results in dilatation of the renal pelvis and calyces. "S12C Fig inS1 File also shows that the Naa10-/Y mouse presenting with hydronephrosis also had an enlarged bladder." (PMID 38713657, 2024). "Hydronephrosis (red arrow, Naa10+/Y 0/23, Naa10-/Y 14/29, Naa10+/+ 0/5, Naa10-/- 7/19) and abnormal genitalia (black arrow) of male (middle, Naa10+/Y 0/23, Naa10-/Y 16/29) and female (bottom, hydrometrocolpos, Naa10+/+ 0/5, Naa10-/- 7/19) are shown." (PMID 34355692, 2021). "S12C Fig in S1 File displays hydronephrosis in a Naa10-/Y mouse." (PMID 38713657, 2024). "The hydronephrosis phenotype was observed in 27% (3/11) of surviving Naa10-/Y mice." (PMID 38713657, 2024). "Out of 32 Naa10-/Y that survived past the third day of life and which were then examined longitudinally, about 60% survived past 200 days of life (~7 months), with some of these then developing hydronephrosis (middle)." (PMID 34355692, 2021).
metastatic tumor (2 papers, 2020). "They showed that the level of NAA10 protein in breast carcinoma patients was distinctly related to lymph node metastasis, with 94.0% (47/50) of metastatic tumor showing increased expression, as compared to 6.0% (3/50) of non-metastatic tumors." (PMID 33126484, 2020). "Furthermore, expressions of Naa10 transcripts were significantly higher in metastatic tumors than in primary PCa tumors (GSE21034) (p < 0.0001)." (PMID 32719332, 2020).
oral squamous cell carcinoma (2 papers, 2022). "In order to evaluate the therapeutic effects of OMVs-MSN-5-FU on the animal model of oral squamous cell carcinoma, the levels of Naa10 and lymphocyte subgroups in the peripheral blood were factored into." (PMID 35515126, 2022). "However, the role and mechanism of NAA10‐mediated invasion and metastasis in oral squamous cell carcinoma (OSCC) remains undetermined." (PMID 35366056, 2022).
pancreas cancer (2 papers, 2025). "Similarly, NAA10|NAA11 was only a hit in melanoma lines and never in lung or pancreas cancer models." (PMID 40968372, 2025).
Astigmatism (1 paper, 2022). A type of refraction error associated with abnormal curvatures on the anterior and/or posterior surface of the cornea. "Visual impairments, such as central or cortical visual impairment, astigmatism or strabismus, appear to be a frequent phenotype occurring in half of all individuals with NAA10 missense variants." (PMID 35039925, 2022).
atrial septal defect (1 paper, 2021). Interauricular communication is a congenital malformation characterized by a communication between the atrial chambers of the heart. "Also, at E18.5, Naa10-/Y embryo shows atrial septal defect (ASD)." (PMID 34355692, 2021).
Barrett esophagus (1 paper, 2022). Esophageal lesion lined with columnar metaplastic epithelium which is flat or villiform. "To further evaluate this possibility, we compared the methylation levels at CpG islands on the NAA10 gene locus of normal squamous (NS), Barrett’s esophagus (BE), and EAC from a methylation screening dataset, GSE104707." (PMID 36433943, 2022). "Moreover, higher NAA10 expression was also confirmed in EAC specimens compared to Barrett’s esophagus, the common precancerous status of the esophagus." (PMID 36433943, 2022).
developmental disabilities (1 paper, 2025). "Recent genetic studies have identified mutations in the NAA15 gene in dozens of individuals, leading to NAA15-related syndrome, which shares clinical similarities with NAA10-related syndrome despite exhibiting variable degrees of developmental disabilities." (PMID 40558489, 2025).
dilated cardiomyopathy (1 paper, 2024). Cardiomyopathy which is characterized by dilation and contractile dysfunction of the left and right ventricles. "Our patient III:8 died from complications related to severe dilated cardiomyopathy (DCM), which has not been previously associated with NAA10-related syndrome." (PMID 39070617, 2024).
esophageal cancer (1 paper, 2022). A primary or metastatic malignant neoplasm involving the esophagus. "We found that NAA10 expression was transcriptionally regulated by the critical oncogene c-Myc in esophageal cancer." (PMID 36433943, 2022). "Higher NAA10 expression also correlates with poorer survival of esophageal cancer patients." (PMID 36433943, 2022). "NAA10 is more highly expressed in esophageal cancer tissues compared to normal tissues." (PMID 36433943, 2022).
Hemihypertrophy (1 paper, 2021). Isolated hemihyperplasia is a rare overgrowth syndrome characterized by an asymmetric regional body overgrowth, involving at least one limb, and associated with an increased risk of developing embryonal tumors principally nephroblastoma (see this term) and hepoblastoma. "Interestingly, the females harbouring the NAA10 c.303C>A and c.303C>G p.(N101K) variants display hemihypertrophy, which has not previously been described for any individuals harbouring pathogenic NAA10 variants." (PMID 32973342, 2021).
Jeavons syndrome (1 paper, 2025).
lymph node metastasis (1 paper, 2020). "Overexpression of NAA10 is associated with microvascular invasion, lymph node metastasis, and lower survival rates in various malignancies, including BCa, LCa, HCC, and osteosarcoma." (PMID 33126484, 2020). "In those malignancies, higher expression levels of NAA10 are correlated with better clinical outcomes; better survival, smaller tumor volume, and lower rates of lymph node metastasis." (PMID 33126484, 2020).
melanoma (1 paper, 2025). A malignant, usually aggressive tumor composed of atypical, neoplastic melanocytes. "In contrast, in melanoma models NAA11 is highly expressed and NAA10 is not individually essential, but in these models the combined disruption of NAA10/NAA11 causes a significant growth defect." (PMID 40968372, 2025).
osteosarcoma (1 paper, 2020). A usually aggressive malignant bone-forming mesenchymal neoplasm, predominantly affecting adolescents and young adults. "Osteosarcoma patients with more than average levels of NAA10 expression showed significantly shorter overall survival, an implication that enhanced NAA10 expression is associated with poor prognosis." (PMID 33126484, 2020).
situs inversus (1 paper, 2021). A congenital condition in which there is complete right-to-left reversal of the position of the major thoracic and abdominal organs (that is, they are arranged in a mirror image of the normal positioning). "We also examined surviving adult mice for any possible situs inversus, but we did not observe this in any adult (>4 weeks) Naa10-/Y mice examined (n = 19)." (PMID 34355692, 2021).
ventricular septal defect (1 paper, 2021). The presence of a defect (opening) in the septum that separates the two ventricles of the heart. "Naa10-/Y embryo shows a ventricular septal defect (VSD) at E14.5 and E18.5." (PMID 34355692, 2021).
viral infection (1 paper, 2017). "The role of hyperacetylation on Naa10 and MYST2 is unknown, and there has been no previous link between these proteins and viral infection." (PMID 29135940, 2017).
cancer (18 papers, 2014 to 2025). A tumor composed of atypical neoplastic, often pleomorphic cells that invade other tissues. "To further clarify the role of NAA10 in human cancer, we analyzed genome-wide loss-of-function screening datasets across a broad panel of tumor cell lines representing multiple cancer types." (PMID 40558489, 2025). "Studies have shown that NAA10 dysregulation can be pathological in humans, and NAA10 has been associated with several human cancers both as an oncoprotein and tumour suppressor depending on the cancer type." (PMID 35039925, 2022). "Recently, dysregulation of NAA10 has been reported to be associated with various human cancers, such as colorectal, breast, lung, and prostate." (PMID 26646451, 2016). "Since works by our group and others have shown that NAA10 is highly expressed at both the mRNA and protein levels in various cancers, we first investigated the cis-association among copy number variation, mRNA expression, and protein abundance of NAA10 using the CPTAC dataset." (PMID 40558489, 2025). "In this review, we summarize the structure of NAA10, its molecular and biological functions in normal development, its involvement in human diseases, and its role in cancer progression." (PMID 40558489, 2025). "It is important to recognize that targeting NAA10 in cancer presents unique challenges due to its functional duality, tissue-specific roles, and involvement in complex regulatory networks." (PMID 40558489, 2025). "Beyond its role in development, NAA10 has emerged as a significant player in cancer biology over the past two decades." (PMID 40558489, 2025). "To further narrow down the most relevant and likely direct targets of NAA10 in cancer, we merged these 123 and 46 proteins with the 173 N-terminally acetylated proteins identified in A431 cancer cells following siRNA knockdown of both NAA10 and NAA15." (PMID 40558489, 2025). "To determine the expression patterns of NAA10 across a large cohort of cancer samples, we analyzed its expression changes in tumor versus normal tissues using data from the TCGA and CPTAC datasets." (PMID 40558489, 2025). "In this review, we summarize the structure, molecular mechanisms, and physiological functions of NAA10, as well as its roles in human diseases and cancer." (PMID 40558489, 2025). "Functioning as a NAT, NAA10 has been shown to mediate N-terminal acetylation of a set of proteins identified in cancer cell line models." (PMID 40558489, 2025). "Our integrated analysis of large-scale cancer datasets, along with multiple published studies, demonstrates that NAA10 is highly expressed at both the RNA and protein levels across various cancer types, strongly supporting its role in promoting tumorigenesis." (PMID 40558489, 2025). "Functional studies implicate NAA10 in regulating cell cycle progression, apoptosis, migration, and other hallmarks of cancer." (PMID 40558489, 2025). "We present in silico analyses of The Cancer Genome Atlas (TCGA) and Clinical Proteomic Tumor Analysis Consortium (CPTAC) pan-cancer data to highlight the clinical significance and potential downstream targets of NAA10 in human cancers." (PMID 40558489, 2025). "This overexpression correlates with aggressive cancer phenotypes and poor prognosis, positioning NAA10 as a potential marker and therapeutic target." (PMID 40558489, 2025). "Although previous studies have shown that NAA10 can function as either an oncogene or tumor suppressor depending on the cancer context, accumulating evidence suggests that it predominantly acts as a cancer promoter in most tumor types." (PMID 40558489, 2025). "In cancer, NAA10 is frequently overexpressed or genomically amplified, where its dysregulation correlates with tumor aggressiveness and poor prognosis." (PMID 40558489, 2025).